IFNG (interferon gamma)
Diseases named in the same sentence as IFNG in open-access papers (continued):
Sharing a sentence is not in itself a finding about the gene and the disease.
experimental autoimmune encephalomyelitis (continued). "Treatment with recombinant HSPB1 has shown translational potential, reducing the paralytic symptoms when injected intraperitoneally in the experimental autoimmune encephalomyelitis mouse model, alongside decreased levels of the inflammatory cytokines IL-2, IL-6, and IFNγ." (PMID 38507480, 2024). "This suppression has also been further emphasized in other disease models where IFNγ blockade even led to an exacerbation of disease by increasing Th17 immune responses, e.g., in experimental autoimmune encephalomyelitis, collagen-induced arthritis, or experimental autoimmune uveitis." (PMID 29416538, 2018). "Whether PGE2 and other prostanoids are the eventual effector molecules of IFNγ’s protective role in collagen-induced arthritis and experimental autoimmune encephalomyelitis remains to be investigated." (PMID 28954232, 2017). "However, more recent evidence suggests that IFNγ may facilitate neuroprotection during chronic stages of MS and in an animal model of MS, experimental autoimmune encephalomyelitis (EAE)." (PMID 37828609, 2023). "It was concluded that in an experimental autoimmune encephalomyelitis (EAE) animal model, probiotics such as Bifidobacterium, Prevotella, and Lactobacillus can decrease the T helper 1 (Th1)/Th17 ratio while inducing interferon gamma (IFN-γ) and interleukin (IL)-17 levels." (PMID 40273120, 2025). "In the experimental autoimmune encephalomyelitis (EAE) model, the transcription of Th1 and Th17-specific cytokine genes interferon gamma (Ifng) and interleukin 17A (Il17a) was upregulated in optic nerve, and decreasing Ifng expression had a protective effect on optic neuritis in EAE mice." (PMID 38375484, 2024). "In MS animal models, when experimental autoimmune encephalomyelitis (EAE) was induced in germ-free mice, a decrease in inflammatory interferon-gamma (IFN-γ) and interleukin-(IL)-17A levels in the CNS was detected, as well as an increase in regulatory T cells (Treg) in the gut mucosa." (PMID 33925359, 2021).
myeloma (109 papers, 2010 to 2025). "In addition, another recent study identified that an IFNγ gene signature is associated with response to selinexor in multiple myeloma patients, pointing toward a possible NK cell involvement." (PMID 36560403, 2022). "In MM patients, however, a high level of IFNG has been shown to be independently correlated with patient survival;59 increased frequency of IFN‐γ+TNF+ CD8+ BM T cells was associated with the profound immune‐driven control of myeloma in a BM transplantation model." (PMID 34845849, 2021). "These multi-peptide-specific T cells, stimulated by multi-peptides, resulted in an overexpression of TAAs in multiple myeloma, and they were capable of producing interferon-gamma (IFN-γ), granzyme B, and perforin, serving as surrogates of cytolytic activity." (PMID 39294656, 2024). "Clinically, IFNγ has demonstrated T cell-enhancing properties to inhibit tumor proliferation in cancers such as multiple myeloma and melanoma." (PMID 38472211, 2024). "The cytotoxic capacity of these genetically engineered NK cells remained even after co-culture with IFNγ pre-treated myeloma cells with increased HLA-E expression." (PMID 36560403, 2022). "Using a prospective study of myeloma patients in the UK Rudy study cohort, we assessed humoral and interferon gamma release assay (IGRA) cellular immune responses to COVID‐19 vaccination post second COVID‐19 vaccine administration." (PMID 35064676, 2022). "Atorvastatin was demonstrated to inhibit phosphorylation of STAT1 imposed by IFNγ in mononuclear cells of multiple myeloma patients; hence, we were convinced to find its effect on PD-L1 expression in HepG2 cells in this study." (PMID 34445462, 2021). "The parent myeloma cell line, U266, showed the lowest IFNγ and perforin releasing responses in stimulated cultures." (PMID 31428094, 2019). "IFNγ production and T cell proliferation induced by autologous myeloma cells is well documented, and we found that PD1+ autologous CD8+ T cells proliferated in response to APC from the bone marrow." (PMID 30174794, 2018). "Following treatment with BI836909, selective lysis of BCMA-positive myeloma cells, activation and proliferation of T cells, as well as release of multiple key cytokines related to effector T cell function (IFNγ, IL-2, IL-6, TNFα, IL-10) were noted." (PMID 31548533, 2017). "According to T-bet expression, the percentage of IFNγ-expressing cells was higher in unstimulated samples of myeloma patients compared to healthy donors." (PMID 27809856, 2016). "TGF-β and IL-10 secreted from myeloma cells mediate the defective DC function, which could be restored by IL-12 and interferon-gamma (IFN-γ).Indoleamine 2,3-dioxygenase(IDO) is produced by immature DCs and can deactivate T cells." (PMID 37275861, 2023). "20, displaying persistently positive MaMs responses, we performed a similar MaMs Cytokine Secretion Assay (CSA) coupled with multiparametric flow cytometry, to further characterize myeloma-specific IFNγ-producing T cells by assessing their surface phenotype and memory T-cell profile." (PMID 36765928, 2023). "Such protective anti-myeloma immunity was clone-specific and mainly conferred by IFNγ-secreting CD8+ T cells, also being further enhanced by a CD137 agonist and IL-17A inhibition, thus representing a potential therapeutic approach to improve the autologous graft-versus-myeloma effect." (PMID 35563634, 2022). "However, IFNγ-induced PD-L1 expression in multiple myeloma cells is mainly through MEK/ERK pathway, while the JAK-STAT pathway shows only a weak influence and PI3K/AKT and NFĸB pathways show no influence at all." (PMID 34445462, 2021). "We sought to determine whether intracellular staining for IFNγ production in CD19 CAR-T after coculture with myeloma cells could be used as a surrogate assay to test for the presence of CD19low myeloma cells instead of dSTORM microscopy." (PMID 31316055, 2019).
myeloma (continued). "However, the IFNγ assay only worked in two of the ten patients that we had shown to contain CD19-positive myeloma cells by FC and dSTORM." (PMID 31316055, 2019). "Liu reported that interferon-gamma (INF-gamma) is a potent inducer and that multiple myeloma cells exhibited exaggerated upregulation of PD-L1 under INF-gamma induction as compared to normal plasma cells." (PMID 31245191, 2019). "An IgG-based BCMA-T cell bispecific antibody (EM801) also increased CD3+ T cell/myeloma cell crosslinking, followed by CD4+/CD8+ T cell activation, and secretion of interferon-gamma, granzyme B, and perforin A." (PMID 31548533, 2017). "Increased levels of key cytokines have also been shown to progressively increase from controls to smouldering myeloma to multiple myeloma including CXCL8 (IL-8), IL-10, TNFα, IL6 and IFNγ." (PMID 28389623, 2017). "Vaccination resulted in the expansion of myeloma-specific T cells in a majority of patients as manifested by the percent of CD4 and/or CD8 T cells expressing IFNγ following ex vivo exposure to autologous tumor lysate." (PMID 25386340, 2014). "To directly assess the anti-myeloma functionality of CD8+ T-cells, we tested the ability of BM-derived CD8+ T cells from healthy or myeloma-bearing mice to kill MOPC315.BM cells in vitro and to secrete IFNγ." (PMID 40644988, 2025). "Ligation with elotuzumab, a humanized anti-SLAMF7 mAb approved to treat relapsing multiple myeloma, promotes NK cells degranulation and IFNγ production after 18h, whereas no significant NK cells activation was observed at 6h of stimulation in HC." (PMID 33828555, 2021). "In summary, these data show that conventional detection (by FC) and analytical methods (by IFNγ secretion assay) are not sensitive enough to reveal CD19low expression on myeloma cells." (PMID 31316055, 2019). "Interaction of myeloma cells with bone marrow stromal cells (BMSCs) via some key factors (SDF-1, TGFβ, IFNγ, IL6, and TNFα, etc.), induces pleiotropic anti-apoptotic mechanisms, thereby rendering multiple myeloma cells resistant to established therapeutic regimens." (PMID 28032590, 2017). "Interestingly, further in depth analyses of T-bet and IFNγ expression in T cell subsets revealed a significant decrease in the CD45RA+ CD8+ T cell compartment (Tn and Temra) of myeloma patients, whereas expression in CD45RA− CD8+ T cells (Tcm and Tem) was similar in healthy and myeloma people." (PMID 27809856, 2016).
cervical carcinoma (108 papers, 2003 to 2025). A carcinoma arising from either the exocervical squamous epithelium or the endocervical glandular epithelium. "Correlation analysis indicated that IDO1 expression in cervical cancer was associated with IFNG expression and the correlation coefficient was estimated to 0.63." (PMID 33390854, 2021). "In silico and in vitro experimental analyses demonstrated that IFNγ treatment could reverse the cervical cancer hallmark and induce cell cycle arrest and apoptosis." (PMID 28526810, 2017). "Also, gene-gene interaction between CD28 and IFNG could increase females’ susceptibility to cervical cancer." (PMID 33160404, 2020). "Interferon-gamma played dual roles in the anti-tumors immunity for many cancer types including cervical cancer, and was related to the efficacy of immune-therapy and radiotherapy." (PMID 40458391, 2025). "Polymorphism genes such as CD28 (rs3116496), IFNG (rs2430561), Pre-miR (rs11134527), and LAMB3 (rs2566), along with DNA-repairing SNPs, affect individual susceptibility to cervical cancer." (PMID 40649795, 2025). "On the mRNA level, high PD-L1 expression in cervical cancer is either accompanied by high interferon gamma activity as a sign of an ongoing T-cell response or by low interferon gamma activity." (PMID 36831389, 2023). "SPP1 encodes a protein which is a cytokine that upregulates expression of interferon-gamma and interleukin-12, and it is an unfavorable prognostic marker in liver, pancreatic, and cervical cancer." (PMID 34830910, 2021). "Treatment of human cervical cancer (HeLa) cells with different interferons (IFNα, IFNβ, or IFNγ) for 24 h induced the mRNA expression of many of the ISGs of interest." (PMID 32528005, 2020). "HeLa (adenocarcinoma) and SiHa (grade II squamous cell carcinoma) cell lines, which represent the two major histological types of human cervical cancer, were treated with various doses of IFNγ for 72 h, after which cell viability was examined by MTT assay." (PMID 28526810, 2017). "This study sought to investigate the direct anticancer effect of IFNγ on human cervical cancer; therefore, an in vitro IFNγ-treated cell culture model was used." (PMID 28526810, 2017). "In this study, the potential uses of IFNγ-based therapy for cervical cancer were evaluated using bioinformatics approaches." (PMID 28526810, 2017). "Our study not only showed that cell cycle deregulation is an indicator of cervical cancer, it also confirmed that targeting the cell cycle by IFNγ and apigenin kills cervical cancer cell lines by triggering cell cycle arrest and apoptosis." (PMID 28526810, 2017). "We stimulated the PBMCs of eight different HPV16+ cervical cancer patients and detected a secondary proliferative response with production of IFNγ in four patients, three of which was expected based on the earlier conducted LST." (PMID 27619514, 2016). "STAT1/IRF-1 pathways initiated by IFNγ had been shown to be important in TNFα and IFNγ synergism in inducing cervical cancer cell apoptosis." (PMID 27342639, 2016). "We show that the TLR2-L SLP conjugates induce significant activation of HPV16-specific CD8+ and CD4+ T cells and robust expression of IFNγ and/or IL-2 by ex vivo stimulated tumor-draining LN-derived T cells of cervical cancer patients." (PMID 27564262, 2016). "Other study indicates that miR-155 acts as a positive regulator of interferon gamma (IFN-γ) production and the increase of IFN-γ enhances susceptibility of cervical cancer cells to lysis by tumor-specific cytotoxic T cells." (PMID 25625305, 2015). "In a subsequent study by the same group, genes/regions statistically significantly associated with CIN3 or cervical cancer included viral infection and cell entry genes OAS3, SULF1, and IFNG; the DNA repair genes DU, DMC, and GTF2H4; the EVER1 and EVER2 genes." (PMID 23554684, 2011). "OAS3, SULF1, DUT, and GTF2H4 SNPs were associated with HPV persistence, whereas IFNG and EVER1/EVER2 SNPs were associated with progression to cervical cancer." (PMID 23554684, 2011).
cervical carcinoma (continued). "Values of IFNγ and IL-12 release in cervical carcinoma are comparableto data obtained after initial HR-HPV infection; all other cytokine levelsremain significantly lower." (PMID 18288269, 2007). "In women with cervical cancer, release of IFNγ and IL-12 was of the same magnitude as in HR-HPV-positive women without clinical manifestations." (PMID 18288269, 2007). "A variant allele of IFNG gene coding for interferon-gamma (IFN-γ), which is essential in defense against viruses and intracellular pathogens and induction of immune-mediated inflammatory responses, has also been associated with increased cervical cancer risk." (PMID 35795639, 2022). "In addition, gene expression of cervical cancer specimens reveals an inverse correlation between IFNγ and lymph node metastases." (PMID 36008984, 2022). "IFNG expression was also increased in all stages of cervical cancer." (PMID 33390854, 2021). "Interestingly, high expression of IFNG is reversely correlated with N stage, indicating complicated roles of IFNG in cervical cancer progression." (PMID 33160404, 2020). "The parallel of biological pathways altered between CxCa-DEGs and IFNγ-downregulated genes may imply the clinical benefit of IFNγ-based therapy through targeting cell cycle deregulation of cervical cancer." (PMID 28526810, 2017). "Therefore, combination therapy with apigenin and IFNγ is a promising therapeutic strategy for cervical cancer." (PMID 28526810, 2017). "Therefore, we demonstrate that IFNγ alone or in combination with apigenin is a selective therapeutic strategy for managing different histological subtypes of cervical cancer." (PMID 28526810, 2017). "NK cells have been found to fight against cervical cancer through the secretion of tumor necrosis factor-alpha (TNF-α) and interferon-gamma (IFN-γ)." (PMID 36139618, 2022). "In peptide-based cervical cancer vaccines, the antitumor efficacy was mainly mediated by CD8+ T cells, and the effect was dependent on IFNγ responses." (PMID 33171765, 2020). "Flow cytometry was used to determine the expression of interferon gamma (IFN-γ), Interleukin-22 (IL-22), IL-17 in the peripheral blood of healthy controls (HC), CIN and cervical cancer patients." (PMID 26474968, 2015). "In the present study, it was confirmed that, in addition to HLA-B, IFITM1 regulates a whole set of surface proteins in cervical cancer cells, both with and without dependence on IFNγ." (PMID 40314078, 2025). "In the context of cervical cancer, persistent inflammation, often initiated by human papillomavirus (HPV) infection, leads to the continuous secretion of pro-inflammatory cytokines such as TNF-α, Interferon gamma (IFN-γ), IL-1, and IL-8." (PMID 40218878, 2025). "We observed higher antigen-specific T-cell proliferation in four and increased IFNγ production in five out of the five tested baseline PBMC samples when Nivolumab was present, indicating that PD-1 expression contributed to the immune suppression in patients with cervical cancer." (PMID 28344877, 2017).
HIV-1 infection (108 papers, 2007 to 2025). The type species of lentivirus and the etiologic agent of acquired immunodeficiency syndrome (AIDS). "In addition, HIV-1 infection was associated with poor IFNγ and TNF production by MAIT cells following E. coli stimulation despite long-term cART in line with previous observations." (PMID 36341446, 2022). "However, for the IFNγ gene, allele A, which is associated with low serum levels of IFNγ, and the homozygous AA genotype were associated with HIV-1 infection (P = 0.0172 and P = 0.0336, resp)." (PMID 25802474, 2015). "Interferon-inducible protein-10 (IP-10) and monokine induced by interferon-gamma (MIG) are chemokines recognized as inflammatory biomarkers during HIV-1 infection." (PMID 37920466, 2023). "There are two types of activation, i.e., the classic interferon-gamma (IFN-γ) pathway of M1 macrophages by Th1-type responses is a well-established feature of cellular immunity to HIV-1 infection." (PMID 36016435, 2022). "Our group and others reported that IL17-producing CD4+ T cells (Th17), and in particular, those producing IFNγ and IL17 (Th1/17), were highly susceptible to HIV-1 infection in vitro." (PMID 28241075, 2017). "Given that IFNγ is also produced early during cytokine storms in the acute stage of HIV-1 infection, IFNγ was thought to affect the subsequent development of CTL activities to control HIV-1 load." (PMID 24454311, 2014). "Throughout the acute stage of HIV-1 infection, IFNγ levels in infected adults steadily increase, with a peak approximately 20–24 days post-infection." (PMID 24454311, 2014). "Remarkably, low levels of IFNγ are detected throughout the course of HIV-1 infection correlating with persistently increasing HIV-1 load." (PMID 24454311, 2014). "The direct effect of IFNγ on HIV-1 infection was first evaluated in in vitro studies followed by small scale clinical trials." (PMID 24454311, 2014). "HIV-1 infection resulted in reduced IFNγ secretion following K562 or cytokine stimulation by both NK cell subsets compared to healthy donors." (PMID 24351015, 2013). "We focussed on patients with active TB to overcome the difficulty in controlling for TB exposure in asymptomatic HIV-1 positive individuals for whom HIV-1 infection confounds peripheral blood interferon gamma release assays normally used to identify prior exposure." (PMID 26986567, 2016). "Therefore, high levels of IFNγ stimulate the clonal expansion of CD4+ T lymphocytes to promote the maintenance of a response during the course of HIV-1 infection." (PMID 25802474, 2015). "Interestingly, HIV-1 infection also resulted in a higher frequency of IFNγ secretion and degranulation by CD7+CD56negCD16+ NK cells in unstimulated conditions." (PMID 24351015, 2013). "However, HIV-1 infection resulted in a significant defect in IFNγ secretion in both NK cell subsets and in degranulation in CD7+CD56negCD16+ NK cells compared to CD7+CD56+CD16+ NK cells." (PMID 24351015, 2013). "In line with our results, it has been demonstrated that IL-13 inhibited HIV production in primary blood-derived human macrophages in vitro and that IL-13 and IFNγ secretion by activated T cells in HIV-1 infection was associated with viral suppression and a lack of disease progression." (PMID 31498845, 2019). "Importantly, the reduced percentage and impaired IFNγ production during infection indicate that CD56dimCD16dim NK cells could account significantly for the impaired NK cell response during HIV-1 infection." (PMID 28674534, 2017). "Furthermore, IFNγ responses of T cells are detected throughout the duration of HIV-1 infection." (PMID 24454311, 2014). "The GSEA results revealed that interferon-gamma and interferon-alpha responses were upregulated in all CD4+ T cell subtypes upon HIV-1 infection." (PMID 40838493, 2025). "The capacity of CD161+ CD4+ T cells to produce IFNγ, TNF, and IL-17 was decreased post-HIV-1 infection compared to pre-infection." (PMID 33322496, 2020).